CACNA1H (calcium voltage-gated channel subunit alpha1 H)
Diseases named in the same sentence as CACNA1H in open-access papers (continued):
Sharing a sentence is not in itself a finding about the gene and the disease.
colon cancer (1 paper, 2022). "These include the plasma membrane Ca2+ ATPase (ATP2B4), the purinergic receptor subtype P2RY2A and the calcium channel ORAI1, all upregulated in colon cancer and the calcium voltage-gated channels CACNA1H and CACNA1Cn were found to be downregulated in colon cancer." (PMID 35267511, 2022).
colorectal adenocarcinoma (1 paper, 2022). The most common type of colorectal carcinoma. "Moreover, expression of the majority of the genes (CACNA1H, COL1A1, COL11A1, FZD8, NGFR, SFRP2, WNT2B, and WNT5A) was associated with the ‘mesenchymal’ CMS group 4 in the TCGA (The Cancer Genome Atlas) Colorectal Adenocarcinoma dataset." (PMID 35892888, 2022).
colorectal tumors (1 paper, 2022). "Further, researchers also found that somatic mutations in CACNA1H recur at the site of tumor metastasis, which could be related to immune escape in colorectal tumors." (PMID 35680563, 2022).
congenital amyoplasia (1 paper, 2019). "Taken together, these findings suggest that severe congenital amyoplasia may be related to CACNA1H and would represent a new phenotype associated with mutations in this gene." (PMID 31070086, 2019).
gastrointestinal stromal tumor (1 paper, 2015). "CACNA1H was located in the top 1% of overexpressed genes in clear cell sarcoma of the kidney and in the top 8% of upregulated genes in synovial sarcoma and gastrointestinal stromal tumors." (PMID 26147197, 2015). "CACNA1H showed altered expression in renal cancer, sarcoma, and gastrointestinal stromal tumors." (PMID 26147197, 2015).
genetic generalized epilepsy (1 paper, 2019). A generalized epilepsy that is understood to have a genetic etiology. "Among calcium channel mutations, CACNA1H, a T-type calcium channel subunit called Cav3.2, has shown three missense mutations in patients with genetic generalized epilepsy and has displayed enhanced channel function." (PMID 31185666, 2019).
Hypokalemia (1 paper, 2024). An abnormally decreased potassium concentration in the blood. "In our patient, the administration of doxycycline for treating acute gastroenteritis likely precipitated hypokalemia by enhancing the expression of the mutated CACNA1H gene variant, thereby increasing aldosterone production." (PMID 39803142, 2024).
Macrocephaly (1 paper, 2022). Occipitofrontal (head) circumference greater than 97th centile compared to appropriate, age matched, sex-matched normal standards. "In this study, we describe the functional analysis of a de novo splice site variant identified in the CACNA1H gene in an individual with ASD and macrocephaly who also carries deleterious compound heterozygous missense variants in the RELN gene." (PMID 35668055, 2022).
muscle atrophy (1 paper, 2020). The loss of muscle tissue due to inactivity or disease. "Results of qRT-PCR also serve as evidence of the unchanged levels of mRNAs coding for atrogin-1 and MURF1, important ubiquitin protein E3 ligases in muscular atrophy, further supporting the importance of ERS and autophagy blockade in CACNA1H deficiency-induced muscle atrophy." (PMID 32332705, 2020).
muscular atrophy (1 paper, 2020). "The decreased CACNA1H expression in the PFM of old mice after MVD and the force decline in CACNA1H-deficient muscle revealed that the reduced expression of CACNA1H related to MVD is associated with muscular atrophy and PFD." (PMID 32332705, 2020). "It was also recently reported that the compound heterozygous mutation of CACNA1H led to congenital muscular atrophy, perhaps through dysfunctional Ca2+ signaling." (PMID 32332705, 2020). "With ERS inhibitor analysis, we demonstrate ERS is an upstream signal and could be used as a therapeutic target for CACNA1H downregulation-induced muscular atrophy." (PMID 32332705, 2020).
neuroblastoma (1 paper, 2021). Neuroblastoma (NB) is the most common solid, extracranial childhood tumor. "Next, we tested the efficiency of the two sgRNAs to target the Cacna1h promoter and regulate its activity in neuroblastoma NS20Y cells." (PMID 35069110, 2021).
pancreatic cancer (1 paper, 2021). "We can hypothesize that reduced expression of CACNA1H prevents Ca2+ influx for RASGRF1, which contributes to poor outcomes in patients with pancreatic cancer." (PMID 33431999, 2021).
pheochromocytoma (1 paper, 2024). "We, therefore, performed functional experiments overexpressing rat CACNA1H (rCacna1h) specifically to address if this particular calcium channel influences the electrophysiologic state of PC12 rat pheochromocytoma cells, as well as the overall proteome of these cells." (PMID 38864697, 2024). "Genetic CACNA1H variants are reported, and CACNA1H/CaV3.2 expression was shown to be generally suppressed in pheochromocytoma/abdominal paragangliomas compared to non-tumorous adrenal medulla, with possible relation to epigenetic inactivation and influence of hypoxia." (PMID 38864697, 2024).
stenosis (1 paper, 2024). "Defects in the T‐type calcium channel CACNA1H cause defects in airway smooth muscle formation and its cytoskeletal organization in tracheal stenosis, and pharmacological increase of RhoA activity can partially attenuate these defects in mice." (PMID 39360593, 2024). "Cacna1h mutants exhibit tracheal stenosis, disorganized SM and compromised tracheal contraction." (PMID 39360593, 2024).
tumor (19 papers, 2016 to 2025). "To investigate possible functional effects of CACNA1H variants, we first used the TCGA dataset to compare RNA-Seq profiles between tumor groups." (PMID 38864697, 2024). "This revealed that the M1 hypermethylated tumor group (n = 29) was associated with higher CACNA1H mRNA levels compared to the non-M1 tumors (n = 141) (P = 0.001; Mann–Whitney U-test)." (PMID 38864697, 2024). "It is notable that HLALOH occurred in the samples with recurrent mutations of S-C clonal pattern including KRAS, SYNE1, FBXL2, DNAH11 and CACNA1H, indicating this mutational clonal patter is facilitating tumor cell to escape immune monitor." (PMID 34453042, 2021). "Among the 29 PPGL, 15 samples had weak staining (+), seven showed varied staining with a mixture of negatively and positively stained cells (±), including the two cases with missense CACNA1H variants, and seven cases showed strong staining (++) in the tumor tissue." (PMID 38864697, 2024). "CACNA1H is a T-type calcium channel gene that has been shown to influence calcium influx, which is crucial for tumor cell proliferation and metastasis, including in BRCA." (PMID 40606662, 2025). "Quantification of CACNA1H mRNA expression in the Karolinska cohort showed that the tumor samples had lower expression compared to the adrenal references (P < 0.001, Mann–Whitney U-test)." (PMID 38864697, 2024). "Then, we found that ERS inhibitor UR906 blocked the apoptosis induced by CACNA1H inhibitor, suggesting that CACNA1H downregulation induced the apoptosis of tumor cells by activating ERS." (PMID 37250140, 2023). "VCGG channels, including CACNA1C, CACNA1D, CACNA1F, CACNA1E, CACNA1A, CACNA1G, CACNA1I, showed significantly higher expression in KIRC than normal cases, whereas CACNA1S and CACNA1H showed higher expression in normal than tumor cases." (PMID 36588677, 2022). "Stratifying CACNA1H expression revealed that patients with higher CACNA1H levels show lower survival rates, suggesting its importance in tumour aggressiveness or treatment response." (PMID 34573310, 2021). "The observation of correlations between DNA methylation density across the CACNA1H gene and its mRNA expression could suggest epigenetic suppression as an additional mechanism involved in the tumor-specific suppression." (PMID 38864697, 2024). "Since knockdown of CACNA1H induced tumor cell apoptosis, we further investigated whether CACNA1H was involved in apoptosis regulation through ERS pathway." (PMID 37250140, 2023). "Overall, our results indicated that high levels of NALCN, TRPC1, TRPV2, and CACNA1H could be suggestive of an advanced stage tumor." (PMID 31083561, 2019). "Patients with M0 stage tumors showed only CACNA1H, SLC24A3 and NALCN associated with OS differences, while ATP2A1, ATP13A2, TRPC1, and NALCN proved to be significantly associated with OS in the N1–N3 tumor stage patient subgroup." (PMID 31083561, 2019). "We detected significant downregulation of IRS2 and NT5E in tumor tissues, whereas CACNA1H, CHPF, SDC1 and ATP6AP1 were highly expressed in tumor tissues than in normal tissues." (PMID 36277284, 2022). "Our studies showed that, similar to patient data, the expression of upregulated genes CACNA1H and TMCO1 is increased in GTML tumour tissues compared to the control mice cerebellum tissues." (PMID 34573310, 2021). "The results showed that CACNA1H, IL13RA1, NUP43, PGK1, and SDC1 were highly expressed in tumor samples, while expression of AK3 was significantly decreased." (PMID 34600547, 2021). "CACNA1H gene expression was demonstrated by multiple methodologies to be generally suppressed in PPGL tumor tissue in comparison to the non-tumorous adrenal tissue consisting of both the adrenal medulla and cortex." (PMID 38864697, 2024).
tumor (continued). "By analyzing the GSE62254 dataset, we found a significant association of prognostic CaRG expression with tumor stages for TRPC1, CACNA1H, and TRPM7, while no genes resulted in being significantly associated with tumor stages from the analysis of the GSE15460 dataset." (PMID 31083561, 2019). "However, there is no report on whether CACNA1H participates in tumor progression through ERS." (PMID 37250140, 2023).
cancer (16 papers, 2015 to 2025). A tumor composed of atypical neoplastic, often pleomorphic cells that invade other tissues. "This study showed that CACNA1H (CaV3.2) gene was significantly upregulated in MB tissues compared to normal brain tissues, and its levels were associated with cancer metastasis and patients survival rates." (PMID 35243582, 2022). "The expression of CACNA1H and ORAI1 was downregulated in KRAS-mutated cells, whereas CACNA1C was upregulated in all tested cancer cells." (PMID 35267511, 2022). "Furthermore, the most diversely expressed genes were particularly enriched in MAPK signaling pathway, such as CACNG4, CACNA1E and CACNA1H, which involve in cancer evolution and heterogeneity formation." (PMID 27602771, 2016). "Hence, CACNA1H expression alone does not appear to be sufficient to mediate metastasis and may be more critical for other cancer-associated processes." (PMID 34573310, 2021).
neurodevelopmental disorder (3 papers, 2022 to 2025). A behavioral and cognitive disorder with onset during the developmental period that involves impaired or aberrant development of intellectual, motor, or social functions. "Our results provide further support for the role of CACNA1H in neurodevelopmental disorders and suggest that rare CACNA1H variants may be involved in ASD development, providing a high-risk genetic background." (PMID 35350424, 2022). "CACNA1H is reported to be a strong candidate for ASD as both de novo and inherited rare variants in CACNA1H were identified in individuals with ASD and other neurodevelopmental disorders, and functional analysis showed a significant effect of CACNA1H variants on channel function." (PMID 35350424, 2022). "Our results provide additional support to previous studies implicating CACNA1H in neurodevelopmental disorders and suggest that CACNA1H mutations may be involved in the pathophysiology of ASD." (PMID 35350424, 2022). "Among the gene families implicated in neurodevelopmental disorders, voltage-gated calcium channel genes—including CACNA1A (encoding Cav2.1), CACNA1C (Cav1.2), and CACNA1H (Cav3.2)—are of particular interest due to their central roles in neuronal signaling, excitability, and neurodevelopment." (PMID 40725423, 2025).
respiratory disease (1 paper, 2024). "Cacna1h in an ethylnitrosourea forward genetic screen for regulators of respiratory disease using the mouse as a model is identified." (PMID 39360593, 2024).
CACNA1H also shares sentences with these, for which no sentence is quoted: prostate carcinoma (11 papers); diabetes (9); neuropathic pain (9); diabetic neuropathy (6); neurological disorders (6); idiopathic generalized epilepsies (5); trigeminal neuralgia (5); Pain (4); peripheral neuropathy (4); Arrhythmia (3); cystitis (3); epilepsy syndrome (3); infection (3); medulloblastoma (3); neuropathy (3); type 1 diabetes (3); adrenal hyperplasia (2); amyotrophy (2); bipolar disorder (2); cardiovascular disease (2); Cerebellar atrophy (2); depression (2); Familial hyperaldosteronism type I (2); focal dystonia (2); Hyperglycemia (2); hypertrophy (2); Intellectual disability (2); itch (2); Migraine (2); myopathies (2).
A further 52 diseases each share a sentence with CACNA1H in 2 papers or fewer.